RAB27A (RAB27A, member RAS oncogene family)
Diseases named in the same sentence as RAB27A in open-access papers (continued):
Sharing a sentence is not in itself a finding about the gene and the disease.
colitis (3 papers, 2020 to 2022). Inflammation of the colon. "We then found that DC-derived EVs rescued exacerbated colitis in hematopoietic Rab27a-deficient mice." (PMID 36214220, 2022). "Additionally, histological analysis indicated that Vav-Rab27A cKO had a greater occurrence of epithelial hyperplasia, goblet cell loss, and inflammatory aggregates as reflected in the total histology score, which is common for this model of colitis." (PMID 36214220, 2022). "RAB27A has been implicated in other secretory functions besides exosome secretion; therefore, we tested whether RAB27A-dependent myeloid cell–derived exosomes were involved in the worsened colitis phenotype." (PMID 36214220, 2022). "Having observed a critical role for hematopoietic RAB27A during DSS-induced colitis, we wanted to confirm that this phenomenon occurred in a second model of colitis." (PMID 36214220, 2022). "By generating mouse strains deficient in cell-specific exosome production, we demonstrate deletion of the small GTPase Rab27A in CD11c+ cells exacerbated murine colitis, which was reversible through administration of DC-derived exosomes." (PMID 36214220, 2022). "Of clinical relevance, administration of DC-derived miRNA-containing exosomes was able to rescue Rab27a-dependent colitis phenotypes in mice, and dysregulated RAB27A and miRNA expression was observed in a cohort of patients with IBD." (PMID 36214220, 2022). "There was an increased proportion of CD38+ “M1-like” macrophages and elevated Th17 cells in the colonic lamina propria (cLP) of Vav-Rab27A cKO mice after DSS colitis." (PMID 36214220, 2022). "Collectively, these results indicate a critical role for hematopoietic derived Rab27a in limiting disease during DSS-induced colitis." (PMID 36214220, 2022). "This highlights Rab27a’s importance to this process of suppressing inflammation in the gut during colitis." (PMID 36214220, 2022). "Double knockdown of Rab27A and Rab27B led to interference in protecting mice from T-cell-transfer-induced colitis, which authenticated the crucial role of Rab27-mediated EVs in the treatment of IBD." (PMID 32410847, 2020). "Rab27a functions in myeloid cells to release exosomes that suppress DSS-induced colitis." (PMID 36214220, 2022). "Next, we further characterized the colons of Vav-Rab27A cKO mice after DSS colitis." (PMID 36214220, 2022). "We found that knocking out either Rab27a or Rab27b in the IECs did not affect DSS-induced colitis weight loss." (PMID 36214220, 2022). "Additionally, we saw that in a different model of IBD based on blocking IL-10R, we observed an exacerbated colitis disease phenotype when Rab27a was deleted from CD11c+ DCs and macrophages." (PMID 36214220, 2022). "Finally, we observed a similar shift in macrophage populations in Vav-Rab27A cKO mouse colons similar to DSS colitis, with more “M1-like” macrophages compared with “M2-like” macrophages." (PMID 36214220, 2022). "And Rab27A silencing inhibits inflammatory process in DSS‐induced colitis mice (P < 0.05)." (PMID 32815642, 2020). "To our surprise, yet demonstrating specificity, we also found that Rab27a and Rab27b were dispensable within the IEC compartment during DSS-induced colitis despite high expression in IECs." (PMID 36214220, 2022). "In this study, Rab27A mRNA and protein were proven to be overexpressed in intestinal epithelial cells of UC patients and DSS‐induced colitis mice, compared with control (P < 0.05)." (PMID 32815642, 2020). "To improve our understanding of the functions of Rab27A in UC, we treated DSS‐induced colitis mice with Lv‐shRab27A (Lv‐shRab27A/DSS group), compared with DSS‐induced colitis mice with scrambled shRNA (Lv‐shRNA/DSS group) through intracolonic administration." (PMID 32815642, 2020). "In the present study, we observed that Rab27A mRNA and protein expression levels were increased in both human UC patients and DSS‐induced colitis mice." (PMID 32815642, 2020).
colitis (continued). "More importantly, animal experiments illustrated that ectopic expression of Rab27A promoted the inflammatory process, whereas overexpression of miR‐124‐3p might interfere with the inflammatory effect in DSS‐induced colitis mice." (PMID 32815642, 2020). "We clearly observed defective exosome release from DCs lacking Rab27A, and this was accompanied by increased DSS colitis disease severity." (PMID 36214220, 2022). "Further, we have also ruled out a contribution by Rab27a-dependent, T cell–derived exosomes and Rab27b-dependent, hematopoietic derived exosomes in regulating gut inflammatory responses during DSS colitis." (PMID 36214220, 2022).
leukemia (3 papers, 2020 to 2023). A malignant (clonal) hematologic disorder, involving hematopoietic stem cells and characterized by the presence of primitive or atypical myeloid or lymphoid cells in the bone marrow and the blood. "We found that RAB27B, but not RAB27A, expression was higher in leukemia cells compared with normal cells." (PMID 37317963, 2023).
Obesity (3 papers, 2024 to 2025). Accumulation of substantial excess body fat. "Specifically, research should focus on how these interactions regulate Rab11 or Rab27a and contribute to increased EV secretion in obesity-associated endometrial cancer." (PMID 39414985, 2024). "We identified alterations in EV-regulating proteins (Rab7, Rab11, and Rab27a) in obesity-mediated EC patients, adipose/uterine tissues, and serum samples." (PMID 39414985, 2024). "To investigate the role of sEVs in promoting BC growth and metastasis under obesity conditions, we generated a mouse model with a knockout of Rab27a (B6/J-Rab27a-Cas9-KO)." (PMID 38402239, 2024).
ulcerative colitis (3 papers, 2020 to 2025). An inflammatory bowel disease involving the mucosal surface of the large intestine and rectum. "Compared with the healthy control group, a significant increase in the number of Rab27A+ or Rab27B+ intestinal immune cells can be observed in the colonic mucosa of the active ulcerative colitis group." (PMID 35371265, 2022). "Together, these results demonstrated that Rab27A plays a crucial role in ulcerative colitis progression through regulating the miR‐124‐3p/STAT3/RelA pathway." (PMID 32815642, 2020). "Collectively, these results indicated that knockdown of Rab27A might suppress the biological functions of ulcerative colitis." (PMID 32815642, 2020). "Thus, we concluded that Rab27A stimulates ulcerative colitis progression through binding miR‐124‐3p." (PMID 32815642, 2020). "Furthermore, we clarified that Rab27A stimulated the STAT3/RelA signalling pathway by binding with miR‐124‐3p to promote the progression of ulcerative colitis." (PMID 32815642, 2020). "Taken together, these data indicate that Rab27A is dysregulated in ulcerative colitis." (PMID 32815642, 2020). "Mechanistically, Rab27A could regulate the miR‐124‐3p/STAT3/RelA axis to promote apoptosis and ROS production in ulcerative colitis." (PMID 32815642, 2020). "In addition to the insights into the pathology of this disease, we found a new pathway in the mechanism of UC: Rab27A, by regulating miR‐124‐3p, can activate the STAT3/RelA signalling pathway, which may provide novel therapeutic approaches with great impact in ulcerative colitis." (PMID 32815642, 2020).
atherosclerosis (2 papers, 2025). A disease characterized by the build-up of fatty material and calcium deposition in the arterial wall resulting in partial or complete occlusion of the arterial lumen. "Liver‐specific knockdown of Rab27a significantly reduced the number of exosomes in the mouse plasma and alleviated MAFLD‐associated vascular calcification and atherosclerosis." (PMID 39680681, 2025). "ORO staining of the whole aorta, aortic arch microscopy, and aortic sinus ORO staining showed that inhibition of Rab27a expression in hepatocytes significantly attenuated atherosclerosis." (PMID 39680681, 2025).
autism (2 papers, 2019 to 2021). Persistent deficits in social interaction and communication and interaction as well as a markedly restricted repertoire of activity and interest as well as repetitive patterns of behavior. "The role of Rab27a in the mammalian brain has not been examined, despite previous work showing a critical role of Rab27a in the development of synapses in invertebrates and the association of RAB27A copy number variations with simplex autism." (PMID 33799820, 2021). "Rab27a is an evolutionarily conserved small GTPase that regulates vesicle trafficking, and copy number variants of RAB27a are associated with increased risk of autism." (PMID 33799820, 2021).
cyst (2 papers, 2020 to 2021). A sac-like closed membranous structure that may be empty or contain fluid or amorphous material. "NSMASE2 and RAB27A were mainly expressed in cyst-lining epithelial cells in kidneys from Pkd1RC/RC mice and ADPKD patients as examined by immunofluorescence and immunohistochemistry staining, respectively." (PMID 34315885, 2021). "Together, our results show similar functional requirements of Rab3A, Rab8A, Rab11A and Rab27A compared to what has been previously reported using MDCK cyst models of epithelial lumen formation." (PMID 32569321, 2020).
diabetes (2 papers, 2021 to 2025). "Because intracellular serotonin regulates insulin secretion from pancreatic β cells through serotonylation of Rab3a and Rab27a, mice selectively deficient in serotonin develop diabetes." (PMID 39926388, 2025). "Intracellular serotonin regulates insulin secretion from pancreatic β cells through serotonylation of GTPases (Rab3a and Rab27a), and mice selectively deficient in serotonin develop diabetes." (PMID 39926388, 2025).
diabetic kidney disease (2 papers, 2023). Progressive kidney disorder caused by vascular damage to the glomerular capillaries, in patients with diabetes mellitus. "Our findings highlight the Rab3A/Rab27A system as a key participant in podocyte injury and vesicular traffic regulation in diabetic nephropathy." (PMID 37237503, 2023).
Ewing sarcoma (2 papers, 2020 to 2023). A small round cell tumor that lacks morphologic, immunohistochemical, and electron microscopic evidence of neuroectodermal differentiation. "Upregulated RAB27A, SYTL2, and VWF expression was confirmed in two human ASPS cell lines, ASPS-KY and ASPS1, in comparison with two Ewing sarcomas, two synovial sarcomas, and one osteosarcoma cell line." (PMID 37029109, 2023).
Glucose intolerance (2 papers, 2011 to 2017). Glucose intolerance (GI) can be defined as dysglycemia that comprises both prediabetes and diabetes. "In the present study, we showed that mice deficient in the Rab27a effector, exophilin-8, exhibit glucose intolerance and impaired insulin secretion in vivo." (PMID 28673385, 2017).
HCMV infection (2 papers, 2010 to 2015). "The molecular mechanisms leading to increased levels of Rab27a in HCMV infection are still unclear, as well as their interference with exosome release." (PMID 26393640, 2015). "HCMV infection increased Rab27a expression, and recruitment of Rab27a to membranous strutures at the assembly site." (PMID 21170347, 2010). "Within 1 day after HCMV infection, Rab27a expression was increased 3 fold, while after 5 days expression levels started to decrease somewhat." (PMID 21170347, 2010). "HCMV infection increased the expression of Rab27a, and shifted the distribution from scattered cytoplasmic punctae to sites where new HCMV was assembled." (PMID 21170347, 2010). "Analysis of host cell gene expression during HCMV infection revealed the up-regulation of Rab27a." (PMID 21170347, 2010). "However, given the positive role of Rab27a in extracellular MHC II-containing exosomes and the regulation of immune responses in glial cells, this role of Rab27a in HCMV infection should be further evaluated." (PMID 26393640, 2015).
Hermansky-Pudlak syndrome (2 papers, 2015 to 2017). Hermansky-Pudlak syndrome (HSP) is a multi-system disorder characterized by oculocutaneous albinism, bleeding diathesis and, in some cases, neutropenia, pulmonary fibrosis, or granulomatous colitis. "In addition, there are several syndromic OCA genes which associated with Hermansky-Pudlak syndrome (HPS 1–7), Chediak-Higashi syndrome(LYST), and Griscelli syndrome types 1 (MYO5A) and 2 (RAB27A)." (PMID 25919014, 2015).
hyperglycaemia (2 papers, 2011 to 2026). "However, the identity of ncRNAs selectively loaded into podocyte EVs under hyperglycaemia and the contribution of vesicle-trafficking regulators such as RAB27A to this process remain to be elucidated." (PMID 42032155, 2026).
liver cancer (2 papers, 2023 to 2024). An epithelial or non-epithelial malignant neoplasm that arises from the liver. "We showed that mutated ß-catenin represses expression of SDC4 and RAB27A, two main actors in exosome biogenesis, in both liver cancer cell lines and HCC patient samples." (PMID 39008536, 2024). "Moreover, RAB27A has been shown to regulate the secretion of EVs in liver cancer stem cells and to contributes to the maintenance of stem-like phenotype and regorafenib resistance." (PMID 37495566, 2023).
multiple myeloma (2 papers, 2022). "Recently, it was reported that system Xc− mediated glutamate export enhanced exosome secretion in multiple myeloma and bone marrow stromal cells by upregulating the expression of Rab27a, TSG101, Alix, and VAMP7, thereby contributing to bortezomib resistance in multiple myeloma." (PMID 36320056, 2022).
neuroblastoma (2 papers, 2019 to 2022). Neuroblastoma (NB) is the most common solid, extracranial childhood tumor. "Four Rab27a shRNAs were examined, one of which was confirmed to knockdown Rab27a in mouse Neuro-2a neuroblastoma cells in vitro." (PMID 30816224, 2019).
oral squamous cell carcinoma (2 papers, 2020 to 2024). "RAB27A regulates the S-palmitoylation of EGFR via zDHHC13 in oral squamous cell carcinoma." (PMID 38415253, 2024). "Ras-related protein RAB27A is significantly overexpressed in oral squamous cell carcinoma." (PMID 38415253, 2024).
osteosarcoma (2 papers, 2020 to 2023). A usually aggressive malignant bone-forming mesenchymal neoplasm, predominantly affecting adolescents and young adults. "Knockdown of Rab27a in osteosarcoma cells could decrease the secretion of osteosarcoma exosomes and 143B-Rab27aKD cells lacks the ability of releasing of exosomal N-cadherin and PD-L1." (PMID 33092576, 2020).
pancreatic ductal adenocarcinoma (2 papers, 2015 to 2025). An infiltrating adenocarcinoma that arises from the epithelial cells of the pancreas. "Various RAB genes have been linked to tumors, including RAB27A, which serves as a predictive indicator for pancreatic ductal adenocarcinoma; RAB13 and RAB3D, which are elevated in pan-cancer; and RAB1A and RAB6A, which have significant functions in rectal cancer and bile duct cancer, respectively." (PMID 40177653, 2025). "It has been reported that the patients with high Rab27A expression have a poor overall survival and is an independent prognostic marker for pancreatic ductal adenocarcinoma." (PMID 25823663, 2015).
renal carcinoma (2 papers, 2020 to 2022). A carcinoma arising from the epithelium of the renal parenchyma or the renal pelvis. "Rab27a was detected with remarkable increased level in kidney tissue from CKD patients with proteinuria compared to normal kidney tissue from patients of renal cancer (n = 4) as the controls." (PMID 32641688, 2020).
renal cell carcinoma (2 papers, 2020 to 2024). "For metastatic renal cell carcinoma (RCC), this study examines the mechanisms of cancer metastasis via the RAB27A-regulated secretion of specific miRNAs." (PMID 38685086, 2024). "The mRNA expression levels of RAB27A and RAB27B mRNA were evaluated in eight renal cell carcinoma (RCC) cell lines." (PMID 38685086, 2024).
retinal degeneration (2 papers, 2010 to 2013). Degeneration of the retina. "However the pathology of CHM cannot be explained solely by compromised Rab27a function as the ashen mouse, which lacks functional Rab27a, does not reproduce the retinal degeneration observed in CHM patients or in CHM mouse models." (PMID 23460904, 2013).
squamous cell carcinoma (2 papers, 2021). A carcinoma arising from squamous epithelial cells. "Rab27a and cortactin coordinately promote exosome secretion by stabilizing the cortical actin-rich MVE docking site in the squamous cell carcinoma SCC61, although the Rab27 effector involved in this process is unknown." (PMID 34483204, 2021).
Type 2 diabetes (2 papers, 2013 to 2019). "We have previously shown that the expression of Rab3a, Rab27a and Slp4/granuphilin is altered upon exposure of β-cells to conditions mimicking those encountered in Type 2 diabetes." (PMID 23826383, 2013). "It was recently shown that the expression of multiple genes encoding components of the docking machinery, including Rab3a and Rab27a, were reduced in islets from type 2 diabetics and that the overexpression of these components could promote granule docking." (PMID 31533953, 2019).
X-linked lymphoproliferative syndrome (2 papers, 2019 to 2024). X-linked lymphoproliferative disease is a hereditary immunodeficiency characterized, in the majority of cases, by an inadequate immune response to infection with the Epstein-Barr virus (EBV). "Such genes are SH2DIA, associated with X-linked lymphoproliferative syndrome (XLP) 1; XIAP, associated with XLP2; RAB27A, associated with Griscelly syndrome type 2; LYST, associated with Chediak–Higashi syndrome; and AP3BI, associated with Hermansky-Pudlak syndrome." (PMID 38541872, 2024).
asthenozoospermia (1 paper, 2023). "The proteins RAB10, RAB3D, RAB27A, and MLPH that showed a lower abundance level in asthenozoospermia and a higher abundance level in oligoasthenozoospermia were either Ras-related or were associated with sperm motility and capacitation." (PMID 37048090, 2023).
asthma (1 paper, 2021). "Mice lacking Rab27a, which is highly expressed and activated in asthma, had reduced EPX release in BAL fluid, again supporting roles of GTPases in Eos exocytosis and degranulation." (PMID 33494375, 2021).
autism spectrum disorder (1 paper, 2019). A spectrum of developmental disorders that includes autism, and Asperger syndrome. "The SYTL4 gene is known to directly interact with several members of the RAB family of genes, such as, RAB27A, RAB27B, RAB8A, and RAB3A which are known autism spectrum disorder genes." (PMID 31323913, 2019).
benign prostatic hyperplasia (1 paper, 2021). A non-cancerous nodular enlargement of the prostate gland. "Furthermore, differential quantitative proteomic analysis of patients with PCa and benign prostatic hyperplasia (BPH) showed a significant decrease in FKBP5, FAM129A, RAB27A, FASN, NEFH proteins after local PCa treatment." (PMID 33810357, 2021).
bladder tumors (1 paper, 2022). "RAB27A and KRT6A promote proliferation and adhesion of bladder tumors and negatively correlate with miR-31-5p expression levels." (PMID 36199571, 2022).
blood disease (1 paper, 2021). A disease that occurs in the blood. "The top candidates include TNFAIP3, which has been reported before, but also include other, novel regions, containing genes involved in blood diseases (CYCS), neurological diseases (PRKCH, KCNH5, LRNN1), metabolism (SFRP4, SUMF1), and skin development (ASCL4, RAB27A)." (PMID 34032215, 2021).
brain tumor (1 paper, 2025). "While this is a common challenge of immunotherapy studies, it is noteworthy that there are several emerging links between Rab27a/b and human brain tumors." (PMID 40408475, 2025). "We then surmised that Rab27a/b-dependent changes in the brain tumor vasculature may translate into tumor infiltration with systemically administered anti-OVA/OT-1 effectors to trigger a meaningful antitumor immunity." (PMID 40408475, 2025).